ALB (albumin)
Diseases named in the same sentence as ALB in open-access papers (continued):
Sharing a sentence is not in itself a finding about the gene and the disease.
diabetes (continued). "Finally, our dataset may include patients with comorbidities such as renal disease and diabetes, which may affect lactate and albumin levels." (PMID 38195421, 2024). "Additionally, our study revealed that people with diabetes had significantly decreased serum ALB." (PMID 39026232, 2024). "Quantifying the amount of albumin in urine through urine albumin-to-creatinine ratio (UACR) or urine protein-to-creatinine ratio (UPCR) is a standard method for assessing kidney damage in diabetes, specifically tracking the decline in estimated glomerular filtration rate (eGFR)." (PMID 38791060, 2024). "Albumin and RDW might improve risk assessment for the development of diabetes." (PMID 39125606, 2024). "A large body of evidence supports a link between albumin level, age, BMI, diabetes mellitus (DM), and mortality following aortic valve replacement." (PMID 38740898, 2024). "Recently, we and others identified that genetic variants (single nucleotide variants (SNVs)) in the gene encoding for cubilin (CUBN) – the main albumin-transporter in PTCs – are associated with microalbuminuria and higher urine albumin levels in populations with and without diabetes." (PMID 36926036, 2023). "We evaluated the albumin redox state in the plasma of 52 participants with DM, 26 with type 1 and 26 with type 2 diabetes." (PMID 38003446, 2023). "Therefore, we examined whether c-Maf deletion had similar effects on diabetes, blood glucose levels, creatinine clearance rate (Ccr), osmolar clearance, serum creatinine and UN levels, and urinary albumin levels in STZ-induced diabetic c-MafΔTAM mice." (PMID 36787192, 2023). "However, the median weight, waist circumference, BMI, serum albumin, C-reactive protein, HbA1c, fasting glucose, blood urea, eGFR, and serum lipids of the type 2 diabetes mellitus group were significantly different from those of the control subjects (p < 0.05 for all)." (PMID 37762893, 2023). "Nevertheless, there were still data gaps in this study, with the number of cases insufficient, and essential risk factors (such as glucose peak, fructosamine, glycated albumin, incidence of hypoglycemia, and diabetes medication) were not included in the medium limit of this study." (PMID 37821909, 2023). "A clinical trial included twenty-one normotensive patients with microalbuminuria demonstrated that combined human C-peptide (600 nmol/24 h) and insulin administration for 3 months might improve the kidney function by decreasing the urinary albumin excretion in patients with type 1 diabetes mellitus." (PMID 37033221, 2023). "The proportion of people with disease (diabetes, thyroid problems, coronary heart disease, liver function, congestive heart failure, cancer/malignancy, and depressive symptoms) was higher among those in the highest albumin quartile (Q4) than in the lowest albumin quartile." (PMID 37340352, 2023). "Conformational changes in human serum albumin due to numerous modifications that affect its stability and biological activity should be constantly monitored, especially in elderly patients and those suffering from chronic diseases (which include diabetes, obesity, and hypertension)." (PMID 35056715, 2022). "Rigorous scrutiny of clinicopathological features of COVID-19 infected cancer patients with diabetes especially values of C-reactive protein, lactate, albumin, alkaline phosphate, neutrophils, and regular monitoring of blood glucose levels may play a critical role in the outcome of the disease." (PMID 36059615, 2022). "Patients who also had diabetes, hypertension, proteinuric kidney disease, chronic kidney disease, diverticular disease and gastro-oesophageal reflex disorders had a higher risk of CVD, as do patients with low albumin, raised C-reactive protein and raised International Normalized Ratio levels." (PMID 34980174, 2022).
diabetes (continued). "It is still debatable whether glycated albumin/glycated hemoglobin A1C (GA/HbA1C) ratio is associated with metabolic dysfunction-associated fatty liver disease (MAFLD), and few studies have been conducted in type 2 diabetes mellitus (T2DM)." (PMID 36369095, 2022). "Hypertension was present in 43.8% in the group with albumin < 30 g/L, compared to 24.5% in those patients with higher levels (p: 0.003); on the contrary, no such association was noted for diabetes, although it must be noted that its incidence was considerably lower in the total cohort." (PMID 36289641, 2022). "Microalbumin, Urine Albumin to Creatinine Ratio and C-reactive protein levels mirrored the fasting plasma glucose levels, being substantially higher among in men and women in Class 3, characterised by diabetes, indicating adverse renal function and inflammation." (PMID 36342918, 2022). "In summary, we have found that the incidence of AKI in PNS patients is 28.05%, and for PNS patients with diabetes, pulmonary infection, albumin ≤ 24 g/L, serum creatinine ≥ 90 μmol/L, blood urea nitrogen ≥ 6.5 mmol/L, uric acid ≥ 390 μmol/L, renal tubular casts, they may have higher risk of AKI." (PMID 35247980, 2022). "In patients with diabetes, for example, the use of insulin could affect the level of serum albumin." (PMID 36212479, 2022). "The Atherosclerosis Risk in Communities (ARIC) also found that renal dysfunction, as measured by microalbuminuria and elevated albumin-to-creatinine ratios, was associated with retinopathy, and this association persisted independent of age, presence of diabetes, hypertension, and other risk factors." (PMID 36498694, 2022). "We speculate that this conversion may be related to diabetes, glucose, and serum albumin levels." (PMID 35780279, 2022). "Additionally, after adjustment for age, diabetes mellitus, rGFR, peritonitis, albumin and Kt/V, serum calcium was not a predictor for all-cause mortality." (PMID 35380083, 2022). "On the other hand, glycated albumin/glycated hemoglobin A1C (GA/HbA1C) ratio was first described as an indicator to predict the future changes of HbA1C based on the fact that the changes in GA would precede those of HbA1C in type 2 diabetes mellitus (T2DM) patients." (PMID 36369095, 2022). "Diabetes mellitus (DM) has been identified as an independent risk factor for DES-ISR, and glycated albumin (GA) is closely related to the prevalence of DM." (PMID 36237913, 2022). "However, the patients who had poor renal function were more likely to have lower eGFR and HbA1c, longer duration of diabetes, and poorer results of the urine tests (Urine albumin to creatinine ratio and urine microalbumin) and blood tests related to renal function such as BUN and serum creatinine." (PMID 36498627, 2022). "Thus, diabetes education, routine self-monitoring of blood glucose levels, and determination of serum glycated albumin and C-peptide during each treatment cycle may be beneficial for the early identification of new-onset T1DM." (PMID 36354692, 2022). "In addition, there is a tendency for improvement in parameters of liver health in both groups after BS (levels of GGT, LDL, triglyceride) and parameters for diabetes (glucose and HBA1c levels), while there was a significant decrease in albumin levels in the TG compared to pre-BS." (PMID 36431314, 2022). "Additionally, our model is more accurate than a similar model by Matsubara developed to predict cardiovascular events in MHD patients and that included age, diabetes status, history of CV events, dialysis time per session, and serum phosphorus and albumin levels." (PMID 36389426, 2022). "A logical regression model that adjusts all variables (including age, gender, race, marriage, education level, albumin, hematuria, serum creatinine, glucose, blood urea nitrogen, total protein, uric acid) to determine the effect of metformin use on cardiovascular disease in patients with diabetes." (PMID 35903672, 2022).
diabetes (continued). "Glycated albumin (GA) has recently gained more and more attention as a control biomarker thanks to its shorter lifespan and wider reliability compared to glycated hemoglobin (HbA1c), currently the “gold standard” for diabetes screening and monitoring in clinics." (PMID 36140073, 2022). "Additionally, our data suggest that the association between urinary albumin excretion and vitamin D levels is independent of glycemic control in patients with diabetes." (PMID 34690928, 2021). "In experimental models of diabetes, a reduced reabsorption of albumin in the proximal tubules (PT) was observed as compared to control animals, which could partly be explained by a reduced albumin endocytosis by PT." (PMID 33673215, 2021). "The association remained significant even after adjustment for traditional CVD risk factors such as age, prior CVD history, diabetes, smoking, triglycerides, total cholesterol, CRP, albumin, hemoglobin, and Apo B. Moreover, Apo A1/Apo B may be used as a predictor of the occurrence of future ACS." (PMID 33913384, 2021). "The results of multivariate logistic regression analysis show that the independent risk factors of albumin infusion during the perioperative period of PLIF were stage ≥ 3, severe intraoperative blood loss, preoperative low level of protein, old age, and history of diabetes." (PMID 34717707, 2021). "However, the presence of other blood components, such as albumin and amino acids, as well as the status of any diseases, such as diabetes, may affect the formation of adducts between chemicals and Hb." (PMID 35051044, 2021). "A persistent reduction of estimated GFR below 60 mL/min/1.73 m2 and/or the existence of albuminuria (albumin-to/creatinine urine ratio ≥30 mg/g) in two measurements with at least a 3-month difference is sufficient to make a diagnosis of DKD in a patient with diabetes." (PMID 34198818, 2021). "On the other hand, the serum albumin with short half-life is prone to be influenced by several conditions such as diabetes mellitus, hepatic insufficiency, chronic kidney disease and hypercortisolism, which may in the end have adverse effects on the prognosis of ACC." (PMID 34445989, 2021). "A significant interaction was found between serum calcium and diabetes mellitus (DM), lipoprotein (a) (Lp (a)), and serum albumin." (PMID 33083294, 2020). "Mechanisms to explain lower serum albumin and BMI may involve chronic inflammation, which appears to be a common factor in various diseases affecting the elderly, including cancer, cardiovascular disease, diabetes, cognitive impairment, frailty, sarcopenia." (PMID 31945744, 2020). "Therefore, the aim of the present study was to evaluate the effect of a mixture of fatty acids (FA) with different saturated and unsaturated acids on the affinity of acetohexamide (AH), a drug with hypoglycaemic activity for glycated albumin, simulating the state of diabetes in the body." (PMID 32429512, 2020). "In conclusion, treatment with canagliflozin in addition to teneligliptin decreases urinary albumin excretion, at least in part, through the reduction of blood pressure and improves a variety of metabolic parameters in a glucagon-independent manner in Japanese subjects with type 2 diabetes mellitus." (PMID 32337293, 2020). "Therefore, when adjusting for the patient's age, vascular access, diabetes, serum albumin, and UA variability, we found that this trend of influence only existed in all-cause death (p for trend = 0.001), while it did not exist for cardiac death (p for trend, 0.003-0.101)." (PMID 32076464, 2020). "In addition, our results are consistent with prior studies that GTT was not related to other factors that could be associated with neuropathy or longer transit times, such as low albumin, diabetes, and obesity." (PMID 32064217, 2020).
diabetes (continued). "Kidney injury, characterized by a progressive decrease in glomerular filtration rate and/or an increase in urinary albumin excretion (UAE), is a frequent complication associated with diabetes mellitus (DM) and hypertension (HTN)." (PMID 32567349, 2020). "However, there were statistical differences in the incidence of diabetes mellitus, BMI, calf circumference, albumin, hemoglobin, and lymphocyte counts among the three groups, being the highest values in the group without malnutrition and the lowest in malnourished group." (PMID 32785121, 2020). "In this large‐scale prospective study, we found that cancer patients with diabetes had a greater body mass yet counterintuitively had a lower handgrip strength, reduced level of serum albumin and poorer performance status when compared with non‐DM patients." (PMID 32813914, 2020). "In this study, we research therelation between preoperative serum albumin levels and postoperative AKIdevelopment in diabetes mellitus (DM) patients undergoing isolated CABG." (PMID 31165612, 2019). "Nε‐(carboxymethyl) lysine‐conjugated bovine serum albumin is an essential component of advanced glycation end products which could damage mitochondrial functions and result in reducing insulin secretion followed by the incidence of diabetes." (PMID 30474315, 2019). "HIV-positive status (adjusted regression coefficient -2.84, CI -5.00–-0.67, p = 0.011), diabetes (adjusted coefficient -2.85; CI, -5.58–-0.12; p = 0.041), and serum C-reactive protein and blood hemoglobin levels were independent predictors of serum albumin levels on multivariable linear regression." (PMID 31181128, 2019). "Interactions were significant between higher mortality rates and lower serum UA, body mass index (BMI), diabetes mellitus (DM), serum albumin and duration of dialysis." (PMID 31170241, 2019). "First, diabetes may result in decreased hepatic albumin synthesis." (PMID 30774722, 2019). "Sixty patients with type 2 diabetes mellitus (DM) were divided into DM group (albumin: Alb <20 mg/L), DN group (Alb >20mg/L), and DN+ MT treatment group, with 20 cases in each group." (PMID 31535033, 2019). "The demographics, type and duration of diabetes mellitus, treatment modality, smoking and alcohol consumption habits, as well as the systemic blood pressure, renal functional tests, hemoglobulin A1c level, serum lipid profile, and 24-h urine albumin level were noted and statistically analyzed." (PMID 29649995, 2018). "IMA (or the albumin cobalt binding test) is used as a novel and sensitive marker of ischemia and oxidative stress mainly for myocardial infarction and various diseases related to ischemia, including peripheral vascular disease, skeletal muscle ischemia, and diabetes mellitus." (PMID 30182924, 2018). "Moreover, we found that serum albumin concentration may differently affect patient survival according to age, status of diabetes, UF volume, serum creatinine level, total cholesterol level, ferritin level, and hs-CRP level." (PMID 29694445, 2018). "However, the ratio of MA among total albumin decreases with age, liver diseases, renal failure, diabetes, and strenuous exercise, and these shifts in the albumin redox state have been attributed to oxidative stress accompanied by these diseases and physical situations." (PMID 30090810, 2018). "Individuals with type 2 diabetes mellitus are at a high risk of developing congestive heart failure, having a relative risk at least twice as high as individuals without diabetes, especially when urinary albumin excretion rate (u-AER) is elevated." (PMID 29850922, 2018). "In this study, we collected urine albumin/creatinine and urine protein/creatinine ratios on obese patients undergoing bariatric surgery to determine the prevalence of albuminuria and proteinuria in obese patients with and without associated diabetes and HTN." (PMID 29761105, 2018).
diabetes (continued). "Furthermore, treatment with CCX140-B, an antagonist to C–C chemokine receptor 2 which monocyte chemoattractant protein-1 binds to, resulted in a reduction in albumin–creatinine ratio, glomerular hypertrophy, and increased podocyte density in experimental diabetes." (PMID 29910771, 2018). "However, higher age, the Charlson Comorbidity Score and incidence of hypertension, diabetes, ischemic heart disease as well as lower albumin level and indices of iron metabolism, were detected in patients with newly diagnosed stroke compared with those without newly diagnosed stroke." (PMID 29141483, 2017). "So inhibition of Amadori-albumin production may be useful to reduce diabetes progression." (PMID 28192530, 2017). "Therefore, the results of this longitudinal analysis indicate that increases in serum albumin concentration might protect against early glycemic deterioration and progression to overt diabetes." (PMID 28430803, 2017). "Patients with lower TA-SUA level tended to have lower body mass index (BMI), phosphorus, serum albumin level, higher proportion of diabetes mellitus (DM), and higher proportion of malnourishment on the subjective global assessment (SGA)." (PMID 27310949, 2016). "Indeed, B6 mice appear to be resistant to various podocyte injuries caused not only by Tns2 deficiency but also by hypertension, diabetes, angiotensin II infusion, HIV-associated nephropathy (HIVAN), albumin overload, renal ablation or congenital nephron reduction." (PMID 27230548, 2016). "This risk is further increased in the presence of elevated CRP and low serum albumin as well as high HbA1c level at the onset of dialysis in agreement with recent reports, suggesting that acute phase reactants and poor control of diabetes worsen the prognosis further." (PMID 27529033, 2016). "Measurements of total glycated serum proteins and glycated serum albumin have been found in various studies, now over three decades, to correlate well with glycated hemoglobin and have been suggested as alternative methods for routine monitoring of glycemic control in patients with diabetes." (PMID 27896233, 2016). "A recent retrospective study reported that eGFR variability could predict death among patients with stage 3 CKD independent of previously well-known risk factors, such as diabetes, proteinuria, serum albumin, baseline eGFR, and eGFR slope." (PMID 27973553, 2016). "Therefore, glycated albumin levels are used as an indicator of diabetes management in Japan." (PMID 27843494, 2016). "Finally, in multivariable analysis, lower eGFR was an independent risk factor for lower serum albumin and higher risk of hypoalbuminemia after controlling for demographics and presence or absence of diabetes mellitus." (PMID 26651991, 2015). "DKD was previously known as diabetic nephropathy and is defined as diabetes with albuminuria (ratio of urine albumin to creatinine ≥ 30 mg/g), impaired glomerular filtration rate (<60 mL/min/1.73 m2), or both and is the single strongest predictor of mortality in patients with diabetes." (PMID 26064987, 2015). "On the other hand, in generalized linear and logistics regression models (dominant and log-additive genetic models) adjusted for age, sex, diabetes status and hypertension, none of the genotypes was associated with serum creatinine, urinary albumin/creatinine ratio or prevalent CKD." (PMID 26112018, 2015). "Thus, we propose a mechanism that, in the early stage of diabetes, a leakage of albumin into the renal tubules upregulates TLR2 and TLR4 and induces HSP70 release and TLR4 activation, leading to a more severe injury and a stronger inflammatory response in the tubule and interstitium." (PMID 26398934, 2015). "Microalbuminuria, which is generally defined as a urinary albumin-to-creatinine ratio (ACR) of 30–300 mg/g, was associated with an elevated risk for cardiovascular disease and death in general population as well as in patients with diabetes mellitus (DM) and hypertension (HTN)." (PMID 25978637, 2015).